FOXP3 (forkhead box P3)
Diseases named in the same sentence as FOXP3 in open-access papers (continued):
Sharing a sentence is not in itself a finding about the gene and the disease.
tumor (continued). "We found significant positive correlation between immunoexpression of PD-L1 in tumor cells and the number of infiltrating Foxp3+ cells in both tested groups of OSCC and between PD-L1 and number of CD4+ cells in OSCCPP group." (PMID 28669079, 2018). "The percentage of CD4+CD25+FoxP3+ Tregs and Gr1+CD11b+MDSCs were significantly increased in tumor microenvironment, and all these were attributed to the upregulation of TGF-β1." (PMID 29301578, 2018). "We found positivity for FOXP3 in 81.8% (9/11) of MF-plaque samples and in 72.7% (8/11) of the MF-tumor cases analyzed." (PMID 29894486, 2018). "We found that NAC treatment significantly decreased the frequency of tumor-infiltrating Treg cells in Senp3+/+Foxp3-Cre mice." (PMID 30089837, 2018). "This combination therapy significantly depleted periphery and intra-tumor FoxP3+ Tregs while increasing intra-tumor CD8+ TILs levels compared to controls or anti-TGF-β monotherapy (p < 0.05)." (PMID 30359281, 2018). "We determined PD-L1 expression, numbers of CD3+ T cells, CD20+ B cells, CD68+ monocytes/macrophages, Foxp3+ regulatory T cells and CD163+ tumor-associated macrophages by immunohistochemistry in 103 patients." (PMID 29190964, 2017). "In line with this negative regulatory role, several seminal studies have demonstrated the prevention of tumor development or regression of established tumors, following efficient and selective depletion of Foxp3+ Tregs." (PMID 29312327, 2017). "IHC revealed increased tumor staining for CD8+ T cells in parallel with a decreased regulatory (Foxp3+) T cell component in animals vaccinated with OX or DOX-treated cells." (PMID 29180759, 2017). "C57BL/6 mice injected intradermally in the ear with B16F10 tumour cells developed solid tumours with steady increases in both absolute numbers and ratios of Foxp3+CD4+ Treg cell population." (PMID 28504276, 2017). "The expression of PD-1 on Tregs correlates with their immunosuppressive activity and the accumulation of PD1+Foxp3+ Tregs within the tumor microenvironment of solid tumors further confirms their immunosuppressive potential." (PMID 29312358, 2017). "The percentage of Th17 cells (CD4+ IL-17+) in tumor-bearing mice was significantly lower, whereas the percentage of Tregs (CD25+ Foxp3+) in tumor-bearing mice was higher at 3, 5 and 7 weeks after LLC inoculation than that in Control." (PMID 29383114, 2017). "To explore the in vivo relevance of above findings, we analyzed the correlation of IL-33 expression with Ki-67 proliferation index (PI), and expressions of arginase 1, IL-10 and FoxP3 in tumor tissues of NSCLC patients." (PMID 28978138, 2017). "FoxP3 is also more likely to be an indicator of tumor-induced immune evasion, since FoxP3+ cells are responsible for inactivation of tumor-specific immune defense and autoreactive T lymphocytes, such as CD8+ cells." (PMID 28885584, 2017). "We next assessed the level of CD25+FoxP3+ Tregs and myeloid-derived suppressor cells in the tumor tissues." (PMID 28489607, 2017). "It has been recently shown that cancers, in which autophagy was upregulated, exhibit higher density of CD8+ T cells and lower number of Foxp3+ T regulatory cells (Treg) in the tumor bed." (PMID 28435516, 2017). "We found FoxP3+ Tregs infiltrating into both intraepithelium and stroma within tumor were significantly positively correlated with 1, 3, 5 and 10-year overall survival (OS), but not with 1, 3, 5-year disease-free survival (DFS) of patients." (PMID 29088871, 2017). "Kaplan–Meier analysis showed that patients with high levels of FOXP3 expression in tumor had shorter overall survival time than those with low levels of FOXP3 expression (P < 0.05)." (PMID 28716029, 2017). "IL-17A and IFN-γ were expressed in the cytoplasm of tumor cells or TILs, FOXP3 was expressed in the nucleus of tumor cells or TILs." (PMID 28537908, 2017).
tumor (continued). "We have already shown that in the murine CAC model CD8+ cytotoxic T cells are crucial for the adaptive anti-tumor immune responses, while Foxp3+ Tregs facilitate immunosuppression." (PMID 28938014, 2017). "A highly significant trend for a longer survival was found in the presence of an increasing number of markers; CD8+ and FOXP3+ T cells, low tumor proliferation and BRAF wildtype status (p = 0.003)." (PMID 28851300, 2017). "The relationship between tumor-infiltrating FoxP3+ Tregs and several clinicopathological features of CRC was also evaluated." (PMID 29209232, 2017). "Significant tumor reduction or eradication is accomplishable by recruiting cytotoxic T lymphocytes, concomitant with downregulation of Foxp3+ T cells." (PMID 29180759, 2017). "Together all these results suggested that RUNX3 play a vital role in FOXP3 transcription in tumor-CD8+ Treg by enhancing the promoter activity." (PMID 28487507, 2017). "In this study, we found that tumor FOXP3 expression was frequently upregulated in NSCLC tissues, and in most cases showed a mixture of cytoplasmic and nuclear expression." (PMID 28716029, 2017). "To investigate if the adaptive immune system was affected by aFP, we measured the number of CD3roup and all survival mice in, CD4roup and all survival mice in, and CD8+ T cells and Foxp3+ Tregs inside the tumor using flow cytometry 5 days after aFP treatment." (PMID 28986576, 2017). "We also evaluated the effect of FOXP3 expression in tumor cells on overall survival and observed that patients with high level of FOXP3 expression in tumor cells survived a longer time than those with low level of FOXP3 expression." (PMID 28029650, 2017). "On the other hand, the presence of CD163+ tumor-associated macrophages, CD4+CD25+ and CD4+FoxP3+ regulatory T cells, and high ratios of regulatory T cells to CD8+ cells were associated with a worse prognosis." (PMID 29137450, 2017). "In conclusion, High density of FoxP3+ Tregs within tumor especially at stromal compartment leads to a favorable outcome in CRC, implicating FoxP3+ Tregs are one of valuable indexes for prognostic prediction in human CRC." (PMID 29088871, 2017). "All these studies provided us novel ideas in searching for further understandings of tumor inhibition via FOXP3/TGF-β/Smad2/3 pathway." (PMID 28903735, 2017). "In this study, we found that the expression of transcription factor FOXP3 was much lower in the spheroids than that in the parental tumor cells." (PMID 28591725, 2017). "In the current report, we provide evidence that E2:ERα complexes drive FOXP3 expression and suppressive function of primary human Treg cells in both healthy male individuals and in tumours from patients with CxCa." (PMID 29229929, 2017). "Associations between IDO1, clinico-pathological features and CD3+, CD8+, CD20+ and FOXP3 tumor-infiltrating lymphocytes were examined using χ2 and Mann-Whitney tests." (PMID 29037255, 2017). "Kaplan–Meier analysis also showed that patients with high levels of FOXP3 expression in tumor had shorter recurrence-free survival time than those with low levels of FOXP3 expression (P < 0.05)." (PMID 28716029, 2017). "Coincidentally, in this study, in addition to FOXP3+ Tregs we also found that there were tissue samples expressing FOXP3 protein in tumor cells." (PMID 28029650, 2017). "By contrast, the frequency of tumor-infiltrating CD4+Foxp3+Tregs with the same TCR specificities as Teffs dropped by over 50% upon the DTA-1 treatment, but the unexpected diversity of their TCRs increased at the levels of amino acid and nucleotide sequences." (PMID 28638937, 2017). "Muscle-invasive bladder cancer (MIBC) patients with FOXP3 expression in tumor cells showed shorter survival compared to those with negative cancers." (PMID 29048388, 2017). "Accumulating evidence suggests that CD4+FoxP3+ Tregs are expanded in various cancers including breast and suppress anti-tumor immunity." (PMID 28388539, 2017).
tumor (continued). "The ratios of tumor-infiltrating CD4+ to FoxP3+ and CD8+ to FoxP3+ were significantly higher in the control group compared to the splenectomy group (8.2 ± 9.3 vs. 2.4 ± 1.5, p=0.046; 2.5 ± 1.4 vs. 1.5 ± 0.4, p=0.031, respectively)." (PMID 29179479, 2017). "An unsupervised hierarchical analysis also identified correlations between CD8+T and Foxp3+ tumor-infiltrating lymphocyte (TIL) densities and average PD-L1 levels." (PMID 29025424, 2017). "New therapies based on reducing or inhibiting FOXP3 expression to reduce abnormal Treg proliferation stabilize the tumor microenvironment and block the immune escape of tumors, and consequently metastasis needs to be discussed." (PMID 28603524, 2017). "CD4+CD25+Foxp3+ Treg cells are key contributors to TGF-β-mediated immunosuppression in tumor microenvironments." (PMID 28002796, 2017). "A high density of FoxP3+ Treg cells infiltrating the tumor stroma is considered a poor prognostic factor in numerous types of tumor." (PMID 28343267, 2017). "Analysis of virus-injected tumours revealed enhanced tumour infiltration with CD4+FoxP3− and CD8+ cells in the animals treated with NDV-ICOSL, which reached statistical significance over the NDV-WT group in the distant tumours." (PMID 28194010, 2017). "IDH1 status was associated with numerically higher plasma macrophage-derived chemokine (MDC/CCL22), higher whole blood FOXP3, and reduced tumor CD3+ T cell counts." (PMID 28481241, 2017). "CD4+CD25+FOXP3+ regulatory T cells (Treg) inhibit the anti-tumour immune response and reduce the effect of cancer immunotherapy." (PMID 28253320, 2017). "Another report demonstrated that an elevated FOXP3/CD8 ratio in tumor tissues was an independent predictor of poor prognosis after RC." (PMID 29048388, 2017). "As compared with the wild type, significant increase of CD4+ Foxp3+ Tregs population was found in the spleen, lymph nodes and peripheral blood of 2cKO tumor bearing mice." (PMID 28592285, 2017). "Meanwhile, A2AR blockade significantly reduced the population of CD4+ Foxp3+ Tregs and enhanced the anti-tumor response of CD8+ T cells." (PMID 28592285, 2017). "We found that in the epithelioid tumours, high CD4+ and CD20+ counts, and low FOXP3+, CD68+ and NP57+ counts linked to better outcome." (PMID 28817839, 2017). "Analysis of lymphocytes isolated from both NDV-injected and distant tumours confirmed the upregulation of ICOS on both CD4+FoxP3− and CD8+ cells." (PMID 28194010, 2017). "In the tumor bed of patients with hepatocellular carcinoma, a FOXP3+CD3+CD4+CD56+ population with immunosuppressive function has been found (similar to regulatory T cells)." (PMID 28791027, 2017). "Median of FOXP3 expression in tumor cells was 3% (range 0-85%) with 39 patients high expression and 59 patients low expression." (PMID 28029650, 2017). "CD4+ T-cells expressing FoxP3 are indicative of regulatory T cells (Tregs) which are thought to promote tumor progression by suppressing antitumor immunity in the tumor microenvironment." (PMID 28923104, 2017). "It is well recognized that cytotoxic CD4+, CD8+ and Foxp3+ TIL constitute the most important effector mechanisms of anti-tumour immunity." (PMID 28322245, 2017). "Concomitantly, increased CD4+ and CD8+ T cell numbers, as well as reduced proportion of CD4+CD25+FoxP3+ (Treg) cells were observed in tumor draining lymph nodes (TdLN)." (PMID 29296231, 2017). "The occurrences of FoxP3+ T cells and Th17 cells replicate the circumstance of the tumor microenvironment, apart from their effector functions." (PMID 29450136, 2017). "Though this finding cannot be simply interpreted as causal relationship between Tregs and better prognosis in CRC, it suggests that FoxP3+ Tregs are effective at delaying tumor invasion and progression." (PMID 29209232, 2017).
tumor (continued). "Here, we performed this meta-analysis to test overall survival (OS) and disease-free survival (DFS) as outcomes in human CRC with known FoxP3+ Tregs density according to the compartment within tumor they invade." (PMID 29088871, 2017). "In mechanism, FOXP3 exerted its tumor inhibition effects probably via the regulation of TGF-β/Smad2/3 pathway." (PMID 28903735, 2017). "There was considerable variation in the total inflammatory infiltrate (INIF) (CD8+ or CD4+ and/or FoxP3+ cells in tumour region) between patients, as well as between different regions within each patient." (PMID 28961847, 2017). "In fact, an accumulation of highly suppressive and activated FoxP3+ Tregs in the tumor tissue of CRC patients has also been reported to correlate with tumor progression." (PMID 29375559, 2017). "There was a strong positive correlation between FoxP3 and Helios expressions in the TME, and CD4+ Tregs co-expressing FoxP3 and Helios were expanded in tumor tissue compared with normal tissue and peripheral blood." (PMID 28388539, 2017). "The dual functions of GATA3 in the regulation of FOXP3 in tumor-CD8+ Treg cells tempted us to understand the molecular mechanisms behind such bi-functional role of GATA3." (PMID 28487507, 2017). "To investigate the immune cells infiltrating tissue microenvironment, we evaluated in paired tumor and non-tumor hepatic biopsies the expression of PD-1 and PD-L1 and FoxP3." (PMID 28837142, 2017). "This resulted in a significant decrease in tumor growth and increased survival, associated with increased T cell tumor infiltration and a reduction in CD4+ Foxp3+ T cells in the tumor microenvironment." (PMID 29371976, 2017). "Of all patients, 53 patients (55.79%) and 57 patients (60%) had increased percentages of Galectin-9+ tumour cells and of Foxp3+ lymphocytes, respectively." (PMID 28871094, 2017). "We examined HLA-A/-B/-C, B2M, and PD-L1 expression on thirty-six NF1-associated tumor samples by immunohistochemistry, and correlated these with tumoral CD4+, CD8+, FOXP3+, CD56+, and CD45RO+ lymphocytic infiltrates." (PMID 29137242, 2017). "Levels of tumor-infiltrating FoxP3+Helios+ Tregs were significantly higher than FoxP3−Helios+ and FoxP3+Helios− Treg subsets." (PMID 28388539, 2017). "Radix Glycyrrhizae polysaccharide (GP) was demonstrated to decrease the mRNA expression of Foxp3 and IL-10 and upregulate Th1/Th2 cytokine ratio in serum in tumor bearing mice, which putatively inhibited tumor growth." (PMID 28804502, 2017). "Flow cytometry showed that the majority of CD4+ tumor-infiltrating lymphocytes (TILs) in M3-9-M tumors have an activated phenotype (CD4+CD25+Foxp3−)." (PMID 28839138, 2017). "That is, we found that patients with a tumor microenvironment (TME) rich in CD163+Foxp3+ CD80+ experience a higher rate of cancer recurrence compared to patients with TME low in CD163+Foxp3+ CD80+." (PMID 28947958, 2017). "We next evaluated the value of tumor cell FOXP3 expression in predicting clinical outcome in a cohort of 240 HCC patients by immunohistochemistry." (PMID 28903735, 2017). "In this context, IL-21 acts a critical opposing force, specifically limiting tumour-mediated FOXP3 induction and preventing suppression of the naïve T cell response." (PMID 28239749, 2017). "The presence of tumor infiltrating lymphocytes (TiLs) and high ratios of CD8+TiLs to FoxP3+ T regulatory cells are associated in EC with a favorable prognosis, as are the presence of CD3+ T cells and CD45RO memory T cells." (PMID 29137450, 2017). "In this meta-analysis, we found FoxP3+ Tregs invading both stroma and intraepithelium within tumor were significantly positively correlated with 1, 3, 5 and 10-year OS, but not with 1, 3, 5 or 10-year DFS in CRC." (PMID 29088871, 2017). "Radiofrequency ablation alone has also been shown to cause a persistent increase in tumor specific antibodies, CD4+ T cells, CD8+ T Cells and to decrease levels of CD25+ FoxP3+ regulatory T cells." (PMID 29037259, 2017).
tumor (continued). "Again, there were significant differences in the percentages of Galectin-9+ tumour cells, Foxp3+ lymphocytes and CD8+ lymphocytes between the paired primary and recurrent NPC." (PMID 28871094, 2017). "Recent studies have demonstrated that increased proportion of tumor-infiltrating FoxP3+ Tregs predict a poor prognosis of patients with cancer, including breast, ovarian, hepatocellular and gastric carcinomas." (PMID 29088871, 2017). "Immunosuppressive cell populations analyzed included Foxp3+ regulatory T cells (Treg cells) and CD163+ tumor-associated macrophages (TAMs), shown to play a crucial role in various cancer types." (PMID 29190964, 2017). "Since CTLA4 is transcriptionally activated by FOXP3, we used this co-stimulatory molecule as a surface signature for the isolation of tumor-CD8+ Treg cells for our study." (PMID 28487507, 2017). "Here, we measured the levels of miR-200c and miR-141 in tumor cells, cell culture medium, and exosomes from FOXP3/GFP-Tet-off MCF7 cells." (PMID 28637482, 2017). "Our study also found that the amount of CD4+CD25+Foxp3+ regulatory T cells in tumor tissue was significantly decreased in SBE treated group." (PMID 28086772, 2017). "We have witnessed a population of CD8+ Treg cells which express high-level of the transcription factor, FOXP3, in the tumor microenvironment." (PMID 28487507, 2017). "FoxP3+ regulatory T cells (FoxP3+ Tregs) are considered to be a key mediator in immune escape and tumor progression." (PMID 29088871, 2017). "Considering the role of immunosuppressive TGF-β signaling in Tregs induction, we assessed the expression of Foxp3 in the tumor site of 2cKO tumor bearing mice." (PMID 28592285, 2017). "The increase in PD-L1 expression in tumor cells can induce Foxp3+ Treg cells increasing the suppression of antitumor T-cell responses and thus allowing tumor progression." (PMID 28079159, 2017). "The mean recurrence-free survival time of the patients with high FOXP3 expression in tumor tissues was 30.5 ± 5.47 months, while those with low FOXP3 expression was 63.8 ± 8.16 months (P = 0.019)." (PMID 28716029, 2017). "To study phenotypic features of Tregs at tumor site, we gated on intratumoral Tregs, and found that most Foxp3+ Tregs belonged to the CD45RA− memory T-cell phenotype." (PMID 28817117, 2017). "Accumulating evidence demonstrated that, in the majority of solid tumors, a high density of tumor-infiltrating FoxP3+ Tregs predicted an impaired patient survival." (PMID 29209232, 2017). "To substantiate tumor suppressive activity of FOXP3, we knocked down and over-expressed FOXP3 in HCC cell lines Hep3B (Hep3B-shFOXP3 and Hep3B-FOXP3, respectively) and 97H (97H–shFOXP3 and 97H–FOXP3, respectively)." (PMID 28903735, 2017). "Flow cytometry analysis of single-cell tumor samples revealed that ~20% of the intratumoral CD4+ T cells were FoxP3+GFP+ Treg cells." (PMID 28496990, 2017). "CEA.Tg mice bearing MC32A tumors and treated with the vaccine alone had significantly higher (*P ≤ 0.05) percentages of Ki67+/CD44+ CD4+FoxP3- T cells in the tumor microenvironment." (PMID 29088720, 2017). "Intense FoxP3+ infiltration correlated with shorter DFS (463 vs. 1193 days) in the group with a lower number of FoxP3+ lymphocytes in the tumor stroma." (PMID 28343267, 2017). "We used immunohistochemistry to measure the expression of Foxp3 in tumor and peri-tumor sites in the lungs." (PMID 29312633, 2017). "The higher FoxP3+ Treg frequencies in the tumor microenvironment are significantly correlated with advanced stage and poor prognosis of CRC." (PMID 29312592, 2017). "PDT effectively depleted tumor infiltrated CD4+ CD25+ Foxp3+ Treg, as well as CD4+ CD25+ Foxp3- T cells that exhibit pathologic features and have a potential to become Tregs." (PMID 28537894, 2017). "We observed significantly higher expressions of IL-33, arginase 1, IL-10 and FoxP3 in NSCLC tumor tissues than adjacent tissues." (PMID 28978138, 2017).